Y_RNA (Y RNA )
Gene: Miscellaneous RNA gene on chromosome 16 (68,885,576 to 68,885,677, reverse strand). Ensembl gene ENSG00000199979.
Homologues: Orthologues: chimpanzee Y_RNA (99% identical). Paralogues in human: Y_RNA (85% identical), RNY3 (82% identical), Y_RNA (82% identical), RNY3P1 (81% identical), Y_RNA (81% identical), Y_RNA (80% identical), Y_RNA (79% identical), Y_RNA (78% identical), RNY3P14 (77% identical), RNY3P2 (77% identical), RNY3P9 (77% identical), Y_RNA (77% identical), and 92 more.